IL6 (interleukin 6)
Diseases named in the same sentence as IL6 in open-access papers (continued):
Sharing a sentence is not in itself a finding about the gene and the disease.
infection (continued). "Recognition of T. cruzi by the innate and adaptive immune cells trigger the production of cytokines, such as IL-1β, IL-18, IL-6, TNF, and IL-10 during the acute phase of infection which exert profound effects in the killing of parasites and in the modulation of inflammation." (PMID 29774028, 2018). "Compared with VR2332c or mock infection, JA142c induced increased levels of type I interferons and pro-inflammatory cytokines (TNF-α, IL-1α/β, IL-6, IL-8, and IL-12) in PAMs, and these elevated levels were comparable to the cytokine induction observed in PRRSV-challenged pigs." (PMID 30509265, 2018). "Similarly to EHDV-TAU infection, the caspase inhibitor Q-VD-OPh rescued cell viability of hMPV-GFP-infected, IL-6-treated LNCaP-JAK1 cells, suggesting the involvement of caspases in the induction of cell death." (PMID 29441069, 2018). "Levels of type I IFNs, TNF-α, IL-6 and CXCL1 as well as CCL2, and IFN-γ were all significantly higher in lungs of 6:2 Tky/05 virus infected mice than in the other three groups at day 2 post infection." (PMID 29300777, 2018). "Co-expression of IL-6 in MHV-68 infection of the mouse lung showed neither significant difference in replication kinetics nor whole lung viral titers in comparison to wild-type virus." (PMID 30486363, 2018). "On a systemic level (plasma) 12 h post-infection IL-6, IL-10, and MCP-1 was higher in TFPI-2−/− mice and no significant changes were observed in INF-γ, TNFα, and IL-12p70, whereas in BALF fluid, IL-10, and MCP-1 was higher in TFPI-2−/− mice." (PMID 30254643, 2018). "Oncolysis in the absence of productive infection, induced by IL-6, correlated with reduction in regulators of cell cycle and metabolism." (PMID 29441069, 2018). "Hence, we quantified the levels of IL-6, TNF-α, and, IL-1β in plasma obtained from intravenous infection model mice." (PMID 30251911, 2018). "However, the levels of IL-6, MCP-1 (CCL2), IL-10, and Arg-1 mRNA were found to be downregulated at 6 weeks post-infection." (PMID 30589840, 2018). "IL-6 on the other hand was produced by both, the hematopoietic and non-hematopoietic compartment in response to infection." (PMID 29782555, 2018). "Also, IL-6 and TNFα has been shown to facilitate infection of resting CD4+ T-cells and to induce productive infection." (PMID 29997630, 2018). "Furthermore, in vitro infection of bone marrow-derived macrophages with E. coli strains ST150 and ST375 induced comparable IL-6 and IL-1β production." (PMID 30356663, 2018). "While the ST1 strain P1/7 and the ST25 strain 89-1591 both induced a variety of cytokines following infection of murine DCs (TNF, IL-6, IL-12p70, and CXCL1), only levels of IL-6 and CXCL1 induced by P1/7 (ST1) were significantly higher than those induced by 89–1591 (ST25) (p < 0.01)." (PMID 30001363, 2018). "While untreated and uninfected LNCaP-JAK1 cells showed only minimal loss of membrane impermeability (~10%), infection (48 h) with EHDV-TAU, in the presence or absence of IL-6, resulted in a significant increase in loss of membrane impermeability (~75%)." (PMID 29441069, 2018). "Although the pDCs were able to produce IL-6 in response to an infection, the levels of this cytokine did not increase following P. brasiliensis stimulation." (PMID 29616019, 2018). "In summary, we found SSC, IL-6 and CD206 increased in the combined Mo and Mo-M of B6.TNF−/−mice, indicating that this population comprises are large proportion of alternatively activated macrophages in B6.TNF−/− mice during L. major BNI infection." (PMID 29403488, 2018). "Interestingly, this study also found that IL-6 and IL-8 were downregulated in the nasal turbinates following infection with pandemic H1N1 virus, which produced a less severe clinical infection compared to the H5N1 in ferrets." (PMID 30135686, 2018).
infection (continued). "Considering that VPA induced a decrease in the production of TNF-alpha and IL-6 in DENV-2-infected PBMCs, we evaluated the effect of this drug on a primary culture of human monocyte-derived macrophages treated 3 h before or after infection with DENV-2." (PMID 29986388, 2018). "We show that in JAK1-expressing cells, IL-6 sensitized PCa cells to viral cell death in the presence or absence of productive infection, with dependence on virus employed." (PMID 29441069, 2018). "Our study supports the hypothesis of a Notch-transduced amplification of inflammation during infection as it reveals a gain of TLR4-primed and NF-κB -mediated expression of IL-6 and TNFα through Notch activation." (PMID 30042932, 2018). "EHDV-TAU-induced oncolysis was also observed in LNCaP-JAK1ΔSTAT3 cells in either absence or presence of IL-6, resulting in productive or non-productive infection, respectively." (PMID 29441069, 2018). "Interestingly, dual deletion of genes 4a and 4b led to a significant increase in the expression levels of IL-6, IL-8, and TNF-α as compared to the wild-type infection." (PMID 29370303, 2018). "PIM/AM-like cells significantly upregulated TNFα expression upon infection, whereas IL-8 and IL-6 were also upregulated, although non-significantly, highlighting the pro-inflammatory role of PIM/AM-like cells upon PRRSV infection." (PMID 29977043, 2018). "Furthermore, plasma levels of inflammatory mediators interleukin-6 (IL-6), CXCL-1, and tumor necrosis factor (TNF) were significantly lower in C5ar1−/− mice than in WT mice at 12 h of infection." (PMID 29362231, 2018). "We found that Mll5−/− PMs had higher gene expression and protein secretion of IFN-β, TNF-α, and IL-6 than their wild-type counterparts had in response to infection with VSV or SeV, but not HSV-1." (PMID 29593341, 2018). "To probe for STAT1 or STAT3 roles in IL-6-mediated inhibition of infection, we tested the effect of IL-6 (5 ng/mL, 14 h) on the knockout cells with or without infection with EHDV-TAU (48 h, multiplicity of infection moi = 0.5)." (PMID 29441069, 2018). "On the other hand, infection of EBV results in the activation of STAT3 and NF-κB signal cascades in target epithelial cells, which induces increased expression of inflammatory cytokines including IL-6 and COX-2." (PMID 29844870, 2018). "In addition, IL-6 was produced by PBMC from all subjects who subsequently developed symptomatic infection, versus 59% of subjects who had subclinical infection." (PMID 30557313, 2018). "One subject with symptomatic infection and four subjects with subclinical infections who did not produce IL-6 in response to DENV-1 did have a response to DENV-4, and one additional symptomatic subject produced IL-6 in response to both DENV-1 and DENV-4." (PMID 30557313, 2018). "In the absence of CHX, IL-6 levels of 128.50% (±26.91%) upon irradiation, 149.96% (±30.98%) upon infection and 114.66% (±19.86%) upon the combination of both were observed." (PMID 30524392, 2018). "However, transcription levels of IFN-β, IFN-λ, ISG56, CCL5, and IL-6, and expression levels of STAT1, pSTAT1, and ISG15 were similar in A549 cells after infection with all 4 recombinant viruses." (PMID 30050872, 2018). "Infection of MPI cells with HK bacteria resulted in the production of IL-6 and IL-1α from 24 h post-infection, in a MOI-dependent manner, while no IL-10 was detected (detection limit estimated to be ~60 pg/mL)." (PMID 29593716, 2018). "STAT3 also partially contributed to EHDV-TAU-induced oncolysis in the presence of IL-6, which occurs in the absence of productive infection." (PMID 29441069, 2018). "IL-6 production was highly up-regulated in DENV-1 stimulated cultures from all but one symptomatic subject, as compared to 17/29 (58.6%) subjects with subclinical infections." (PMID 30557313, 2018). "Live calves had higher plasma concentrations of SAA and IL-6 than dead calves with (PM INF+) or without (PM INF-) in utero infection." (PMID 30382887, 2018).
infection (continued). "We have shown that the initial genomic response to infection of human cells with M. tuberculosis is a short-lived burst with increased production of mRNA transcripts coding for inflammatory cytokines, including TNF-α, IL-6, IL-8, MIP-1α and MCP-1." (PMID 29330469, 2018). "The genes with strongest induction included chemokines (e.g. CXCL11, 84-fold; CXCL10, 18-fold; CXCL9, 9-fold; CCL2, 9-fold) and cytokines (e.g. IL6, 54-fold; IL12B, 10-fold; IL1B, 9-fold;) etc. consistent with the infection of host phagocytes with Mtb reported earlier by us." (PMID 28880895, 2017). "Knockdown of salusin-β with Ad-Salusin-shRNA dose- and time-relatedly reduced salusin-β, IL-1β, IL-6 and TNF-α mRNA levels, and NOX2 protein and 4-HNE levels in HG-treated H9c2 cells, reaching its maximal effects at the multiplicity of infection (MOI)=100 treated for 24 h." (PMID 28333148, 2017). "Notably, 1–2 h after infection, TAGLN2−/− mice showed higher plasma levels of TNF-α, IL-6, IL-1β, and IL-12 than wild-type mice." (PMID 28821818, 2017). "In addition, studies in IL-6−/− mice, revealed the involvement of IL-6 in decreasing the number of DN2 thymocytes after infection." (PMID 28147332, 2017). "For predicting major infection, the AUC for circulating histones was 0·78 (0·62 to 0·94), which was similar to, or lower than the values for BISAP, APACHE II, SOFA, urea, creatinine and IL-6 (range 0·80 to 0·87) within 24 h." (PMID 28436602, 2017). "Since IL-6 mostly functions as a proinflammatory cytokine, E. faecium might reduce inflammation during an ETEC infection." (PMID 28607532, 2017). "We then confirmed that knockdown of the CD147 expression by miR-US25-1-5p could specifically reduce the activation of IFNB1 and interferon-related gene ISG15 and the NF-κB downstream genes IL-6 and TNF-α induced by HCMV early infection." (PMID 29194430, 2017). "Inflammatory response genes, such as NOS2, IL6 and TNFRSF1B, were up-regulated while some positive regulation of inflammatory response genes, such as TLR3, STAT5 and LRRC32, were also elevated post-infection with IBDV." (PMID 28486945, 2017). "IL-1β, IL-6, and TNF-α are proinflammatory cytokines released by activated macrophages, are involved in the upregulation of inflammatory reactions, and are important contributors to the inflammatory response to infection." (PMID 28255203, 2017). "Indeed, hyphae and muriform cells infection induced high levels of TNF-α, IL-1β and IL-6 during the disease establishment stage." (PMID 28355277, 2017). "Rising interleukin-6 typically indicates an unresolved infection/inflammation, while low levels have a high negative predictive value making severe septic infection unlikely." (PMID 28856437, 2017). "In contrast, Breyne and co-workers (2015) reported that infection of the mouse mammary gland with S. aureus resulted in local induction of IL-1β and IL-6 but not TNF-α." (PMID 28129375, 2017). "In the absence of infection, it was observed that enrofloxacin and toltrazuril increased IL-6 production compared to untreated cells (P < 0.05)." (PMID 28798905, 2017). "Moreover, IL-6 and TNF-α levels significantly increased over course of time in both, ethanol-treated mice and respective controls, indicating ongoing infection and progression of disease." (PMID 29348965, 2017). "IL-6 and TNF alpha are involved with the infection inflammation and their levels will be increased." (PMID 28335413, 2017). "In addition, the production of TNF-α, IL-6, and IL-10 was similar between TLR2−/− and WT mice during the early stage of infection (5 dpi)." (PMID 28979269, 2017). "To examine the effect of LG2055 on inflammatory responses in gingival tissues of mice orally administered P. gingivalis, we examined the IL-6 and TNF-α mRNA levels in gingival tissues and GMCs, and IL-6 and TNF-α secretion in GMCs 1 and 30 days after the final infection." (PMID 28373699, 2017).
infection (continued). "Expression of the pro-inflammatory cytokines IL-6 and TNF-α was induced following infection of cells with M. tuberculosis H37Rv, which was significantly (p < 0.05) suppressed by TQ (5 and 10 μg/mL) treatment at the indicated time points, as determined by qRT-PCR." (PMID 28545436, 2017). "The absence of risk factors for infection, presence of septic shock, baseline values of sCD14 and decrease of PCT and IL-6 from baseline to day 5 were variables associated to mortality in the univariate analysis." (PMID 28380034, 2017). "Levels of some chemokines and cytokines, such as MIP-2, MCP-1, IL-6, IL-17A, and IFN-γin colons were significantly attenuated in S100A4−/− mice after C. rodentium infection, which suggested reduced inflammation during early infection." (PMID 28935867, 2017). "Consequently, IL-6 mRNA expression is dependent on the activation of MAPKs p38 and ERK1/2 after infection of A549 cells." (PMID 28195157, 2017). "Concentrations of IL-6 in BALF were almost identical in calves treated with vital or inactivated Cp, while fever (at the investigated time intervals) only occurred in animals suffering from the real infection." (PMID 29281663, 2017). "Multiple inflammatory cytokines, including TNF-α, IL-6, IL-1β, IFN-γ, IL-17, and VEGF, disrupt BBB and TJ integrity in BMECs, and inflammatory cytokine signaling at the BBB during infection facilitates leukocyte trafficking into the CNS, which is essential for the clearance of many pathogens." (PMID 29403485, 2017). "Even in the absence of infection, reporter mRNAs bearing the IL-6 SRE remain stable in SOX-expressing cells, an observation that has helped delineate features of this novel RNA element required for the protective phenotype." (PMID 28841715, 2017). "As determined by ELISA analyses, HSV-2 WT infection strongly enhanced the production of TNF-α, IL-6, IL-8 and CCL2, but the levels of these proinflammatory cytokines and chemokines were inhibited in End1/E6E7 cells which were infected with the Us2 mutant of HSV-2." (PMID 28827540, 2017). "However, TLR2 was involved in expression of the pro-inflammatory cytokines IL-6 and CXCL1 by DCs following infection with S. suis and stimulation by both TLR2 ligands." (PMID 28894449, 2017). "IL-6 was not present in viral inoculum but was found in the ultrapure neutrophil supernatants, indicating that it is released from the neutrophils upon infection." (PMID 28993776, 2017). "Secretions of IL-6 and CCL5 (RANTES) from infected cells were measured following infection." (PMID 28877226, 2017). "However, at day 2 and day 4 after infection, the antiviral IFN-β and proinflammatory IL-6/TNFα response to flu infection was significantly inhibited in CS-exposed WT mice." (PMID 28865477, 2017). "Unlike TNFα, IL-6 is critical to resistance against M. tuberculosis, but it is dispensable for the control of mycobacterial growth after low-dose aerosol-delivered infection." (PMID 28223969, 2017). "Swine IV infection induced interferon (IFN)-alpha and interleukin-6 responses in bronchoalveolar fluids (BALF) at day 3 post infection, as opposed to the other non-swine-adapted virus strains." (PMID 28484702, 2017). "This indicates that up-regulation of IL-6 following infection with mutant parasites regardless of the parasite strain is a hallmark of the HRF gene product, which was shown to directly control IL-6 production." (PMID 28831137, 2017). "Expression of iNOS and pro-inflammatory cytokines (IL-6 and TNF-α) was induced following infection of cells with M. tuberculosis H37Rv, which was significantly (p < 0.05) suppressed by TQ (5 and 10 μg/mL) treatment at the indicated time points, as determined by qRT-PCR." (PMID 28545436, 2017). "Additionally, Trim29-KO mice had higher concentrations of IFN-I, IL-6, and TNF-α in the serum than did their WT littermates after infection with HSV-1." (PMID 29038422, 2017). "Additionally, we compared TNF-α, IL-10, and IL-6 levels between mild and severe cases of ANDV-infection." (PMID 28708900, 2017).
infection (continued). "Notably, we observed upregulated mRNA expression levels of IFNα/β, IL6, TNF and several chemokines as CXCL10 or CXCL11 after USUV infection." (PMID 28873445, 2017). "IL-6 meanwhile is produced rapidly upon initial RSV infection with peak concentrations seen within the first 24 hours, although it remains detectable in the airways for several weeks post infection." (PMID 28953978, 2017). "Despite increased IL-6 mRNA levels after IFNβ stimulation, super-infection with S. aureus 6850 did not additionally increase IFNβ-induced IL-6 synthesis." (PMID 28195157, 2017). "IL-6 synthesis was also significantly dependent upon MOI (PMSS1 p<0.01 by one-way ANOVA; J166 p<0.05 by one-way ANOVA), but both H. pylori strains induced comparable levels of cytokine synthesis in 16-HBE cell cultures following infection." (PMID 28813514, 2017). "When patients were stratified by infection status, we observed increases in TNF-α, CRP, TGF-β, IL-4, IL-6, IL-10, IL-17, and IL-23, and a decrease in IFN-γ in both uninfected and infected patients when compared with control subjects at most of the three time points." (PMID 27682880, 2017). "While the role of IL-6 in RSV infection has not previously been studied, use of IL-6 deficient mice has shown that IL-6 is critical in controlling viral load after infection with either an H5N1 or H1N1 influenza A virus, with mice succumbing to lethal infection in IL-6’s absence." (PMID 28953978, 2017). "ΔN146-infected cells, similar to the LPS-treated cells, expressed and secreted copious levels of type I interferon β (IFN-β), IL-1β, IL-6 and tumor necrosis factor α (TNF-α) 12 h post infection whereas these cytokines were barely detectable in supernatants from mock infected cells." (PMID 28150813, 2017). "Infection of gingival epithelial cells by F. nucleatum increases the expression of antimicrobial peptides and cytokines, such as human beta defensin (HBD)-2, HBD-3, interleukin (IL)-6, and IL-8." (PMID 28748028, 2017). "When combining the positive results of any two tests, we found the probability of infection was 100% (except CRP + IL-6 and IL-6 + ESR) but with low probability of occurrence (the rate among infected nonunion patients was CRP + ESR: 25.7%; CRP + WBC: 17.1%; IL-6 + WBC: 20%; WBC + CRP: 11.4%)." (PMID 29130050, 2017). "Furthermore, changes in type I IFN, IL-6, IL-8, TNF-α, MCP-1 and IP-10 production were observed during concomitant infections." (PMID 28644900, 2017). "Interleukin-6 (IL-6), interleukin-8 (IL-8) and macrophage migration inhibitory factor (MIF) were produced during Huh-7 DENV infection at significant levels in cell supernatants starting from 48 h after infection." (PMID 28591408, 2017). "Neutralization of IL-17 or TNF-α but not IL-6 resulted in accelerated clearance of M. catarrhalis and effectively prevented infection-induced exacerbation of AAI." (PMID 29184554, 2017). "Also, there were onefold to threefold more TNF-α and IL-6 detected in BALF from Trim29-KO mice, as compared to that in WT mice on day 1 or day 3 post infection." (PMID 29038422, 2017). "It has been shown that IL-6, a pleiotropic cytokine, plays a central role in the immune responses activated through the TNF-α and NF-κB pathways, as a first line of defense against infection in the acute-phase response." (PMID 26865111, 2016). "Our results revealed higher mortality rates and bacterial burden after infection in TNFR1−/−, IL-6−/−, and TNFR1-IL-6−/− mice and a decreased immune response including lower neutrophil infiltration in the meninges of TNFR1−/− and TNFR1-IL-6−/− mice in contrast to IL-6−/− and wild type mice." (PMID 27057100, 2016). "Several cytokines produced by T cells (IFNγ or TNF35, 36), myeloid cells (IL-1, IL-12, TNF, IL-6 32, 37, 38, 39, 40) or epithelial cells (GM-CSF41) are ascribed crucial roles in host resistance based on the early mortality of knockout mice following infection." (PMID 27819295, 2016).